MAPK4 (mitogen-activated protein kinase 4)
Diseases named in the same sentence as MAPK4 in open-access papers (continued):
Sharing a sentence is not in itself a finding about the gene and the disease.
glioma (continued). "Moreover, circ‐MAPK4 regulates apoptosis in glioma cells by regulating p38/MAPK phosphorylation level." (PMID 37786890, 2022). "In addition to FBXW7-185aa described earlier, circ-MAPK4 sponges miR-125a-3p to inhibit glioma cell apoptosis via downregulating P38/MAPK phosphorylation levels." (PMID 34745938, 2021). "Taken together, the rescue experiments showed that circ-MAPK4 could maintain glioma cells survival, inhibit their apoptosis, and induce glioma cells invasion." (PMID 31992303, 2020). "In this study, we show that circ-MAPK4 (has_circ_0047688), which is downregulated after neural differentiation in an induction model by stimulation with retinoic acid, but is upregulated in gliomas tissues and cell lines." (PMID 31992303, 2020). "The role of circ-MAPK4 in inhibiting the apoptosis of glioma cells was also shown in vivo." (PMID 31992303, 2020). "In addition, flow cytometry analysis indicated that circ-MAPK4 downregulation inhibited glioma cells survival by inducing cell apoptosis." (PMID 31992303, 2020). "Furthermore, we found that circ-MAPK4 acts as a specific sponge for miR-125a-3p, which is reported to be a tumor-suppressor in glioma." (PMID 31992303, 2020). "Circ-MAPK4 is downregulated during neural differentiation; hence, we hypothesized that it can play a role in the development and progression of gliomas." (PMID 31992303, 2020). "Moreover, in our validation cohort, circ-MAPK4 was elevated in patients with advanced stages of gliomas (III + IV vs I + II, P < 0.05)." (PMID 31992303, 2020). "In this study, silencing of circ-MAPK4 caused levels of the cleaved form of apoptosis effectors (caspse-9, caspase-7, caspase-3 and PARP) increased, suggesting the anti-apoptotic role of circMAPK4 in gliomas progression." (PMID 31992303, 2020). "In experiments, silencing of circ-MAPK4 significantly inhibited survival of glioma cells." (PMID 31992303, 2020). "Furthermore, a significant inverse correlation occurred between circ-MAPK4 and miR-125a-3p in glioma tissues (R squared = 0.2394, P < 0.01)." (PMID 31992303, 2020). "However, the role of MAPK4 in AKT activation, as well as the expression, clinical significance, biological roles and underlying molecular mechanisms through which MAPK4 acts in glioma, is still obscure." (PMID 36999945, 2023). "Additionally, MAPK4 expression correlated negatively with the presence of antitumor immune cells and positively with the expression of immune‐inhibited checkpoint proteins in the glioma microenvironment yielding new insight into the promoting role of MAPK4." (PMID 36999945, 2023). "Therefore, we suggest that circ-MAPK4 may be a promising biomarker and therapeutic target for gliomas." (PMID 31992303, 2020). "Therefore, defects in p38/MAPK function may contribute to oncogenic effect of circ-MAPK4 in glioma cells." (PMID 31992303, 2020). "We hypothesized that circ-MAPK4 may affect gliomas progression." (PMID 31992303, 2020). "Thus, MAPK4 expression may be correlated with immune infiltration of the glioma microenvironment." (PMID 36999945, 2023). "In gliomas, circ-MAPK4 inhibited cell apoptosis and promoted cell proliferation via activating p38/MAPK signaling by sponging miR-125a-3p in gliomas." (PMID 33539420, 2021). "All the results suggest the role of circ-MAPK4 is to downregulate phosphorylation levels of p38/MAPK, which inhibits apoptosis of glioma cells." (PMID 31992303, 2020). "MAPK4 expression was significantly positively correlated with expression of the main immunoinhibitory checkpoint molecules PD‐1, PD‐L1, HAVCR2, PDCD1LG2 and TIGIT in glioma." (PMID 36999945, 2023). "In univariate Cox regression analysis, MAPK4 expression, WHO grade, 1p/19q codeletion and age correlated with overall survival in glioma patients, whereas in multivariate Cox regression analysis, WHO grade, 1p/19q codeletion and age correlated with overall survival." (PMID 36999945, 2023). "MAPK4 was overexpressed in IDH wild‐type (wt) and 1p/19q non‐codeletion gliomas." (PMID 36999945, 2023).
glioma (continued). "Correlation analysis of MAPK4 IHC staining with clinicopathologic parameters was performed, and increased protein levels of MAPK4 were found to be significantly correlated with the WHO grade of glioma." (PMID 36999945, 2023). "Additionally, circ-MAPK4 regulated the p38/MAPK pathway, which influenced the development and apoptosis of gliomas." (PMID 35883576, 2022). "Our findings suggest that circ-MAPK4 is a critical player in glioma cell survival and apoptosis via p38/MAPK signaling pathway through modulation of miR-125a-3p, which can serve as a new therapeutic target for treatment of gliomas." (PMID 31992303, 2020). "We show that circ-MAPK4 is significantly overexpressed in gliomas compared with the non-tumor brain tissues." (PMID 31992303, 2020). "For the others circRNAs found in the neural differentiation model, 9 circRNAs expression profile were examined in our glioma tissues, but no more significantly overexpression were found in glioma tissues like circ-MAPK4." (PMID 31992303, 2020). "Furthermore, we proved that circ-MAPK4 was involved in regulating p38/MAPK pathway, which affected glioma proliferation and apoptosis." (PMID 31992303, 2020). "Considering the dedifferentiation status of glioma, circ-MAPK4 was found, but not the MAPK4 mRNA, to be significantly overexpressed in glioma tissues compared with normal brain tissues as measured by qPCR using divergent primers." (PMID 31992303, 2020). "Glioma cells were transfected with circ-MAPK4 siRNAs, then cell proliferation, apoptosis, transwell assays, as well as tumorigenesis and TUNEL assays, were performed to examine effect of circ-MAPK4 in vitro and vivo." (PMID 31992303, 2020). "Similarly, circ-MAPK4 (259 bp), detected in clinical glioma samples, promotes tumor progression by preventing apoptosis through the suppression of caspase 3/7/9 activation and enhancing p38/MAPK signaling, thereby increasing glioma resistance to therapy." (PMID 40305280, 2025). "The upregulation of p38/MAPK phosphorylation could be slowed down to the extent that circ‐MAPK4‐induced apoptosis in glioma cells did not increase excessively." (PMID 37786890, 2022). "Therefore, we suggested that miR-125a-3p was regulated but not degraded by circ-MAPK4 in gliomas." (PMID 31992303, 2020).
prostate carcinoma (11 papers, 2006 to 2026). A carcinoma that arises from epithelial cells of the prostate gland. "The oncogenic role of MAPK4 in prostate cancer and triple-negative breast cancer was subsequently reported." (PMID 40200093, 2025). "In line with this, MAPK4 overexpression stimulates, whereas its knock-down inhibits the growth of prostate cancer xenografts in vivo." (PMID 36768610, 2023). "Our results are consistent with a recent report that presented evidence that MAPK4 is a novel therapeutic target in prostate cancer, especially castration‐resistant prostate cancer." (PMID 36999945, 2023). "We have previously reported that inhibiting MAPK4 (knockdown or knockout) is very effective in suppressing the growth of various MAPK4-high cancer cells, including breast cancer, prostate cancer, non-small cell lung cancer, and colon cancer." (PMID 37531320, 2023). "Overexpressed MAPK4 was correlated with poor survival in various cancers and played an oncogenic role in prostate cancer." (PMID 35550610, 2022). "Conversely, MAPK4 is regarded as a tumour promoter in some cancers, such as lung adenocarcinoma, colon cancer, and prostate cancer." (PMID 36618768, 2022). "In prostate cancer studies, MAPK4 overexpression promoted prostate cancer metastasis through HSP27 upregulation." (PMID 36618768, 2022). "Other genes whose overexpression was associated with poor survival of breast and prostate cancer patients encode regulators of differentiation (ROD1), protein kinases (MAPK4), and regulators of cytoskeletal organisation (TMSB10)." (PMID 17183660, 2006). "A proliferative effect of MAPK4 was also observed in prostate cancer PC3 cells." (PMID 36618768, 2022). "MAPK4, members of signaling pathways involved in the development of MM, has been identified as a tumor suppressor that is down-regulated and in various adenocarcinomas or cancers, such as pancreatic adenocarcinoma, breast and prostate cancer." (PMID 30728056, 2019). "MAPK4 has been reported to be an oncogenic gene in triple-negative breast cancer (TNBC) and prostate cancer, and similar results were also found in NSCLC cells." (PMID 40200093, 2025). "Mitogen‐Activated Protein Kinases 4 (MAPK4), a non‐classic MAPK, is highly expressed in kinds of malignancies, such as prostate cancer, breast cancer and cervical cancer." (PMID 40845073, 2025). "MAPK4 also enhances AR function via the stimulation of GATA2 gene expression and protein stability, thus leading to increased prostate cancer cell proliferation." (PMID 36768610, 2023). "MAPK4 promotes the proliferation of colon cancer and lung cancer by noncanonical AKT/mTOR,10 while MAPK4 facilitates prostate cancer growth and castration resistance by activating the GATA2/AR and AKT pathways in parallel." (PMID 36999945, 2023). "Emerging evidence indicates that MAPK4 regulation of the AKT signalling pathway may be involved in the pathogenesis of tumours, such as lung adenocarcinoma, colon cancer, and prostate cancer." (PMID 36618768, 2022).
gastric cancer (10 papers, 2013 to 2025). A primary or metastatic malignant neoplasm involving the stomach. "Depletion of mitogen-activated protein kinase 4 (MAPK4) in gastric cancer cells is associated with macrophage polarization to tumor-associated macrophages (TAMs)." (PMID 40034694, 2025). "Our data show that MAPK4 downregulation in gastric cancer tissues is significantly associated with liver metastasis and poor prognosis in patients." (PMID 36797541, 2023). "In this study, we found that MAPK4 downregulation in gastric cancer tissues from patients is significantly associated with liver metastasis and poor prognosis." (PMID 36797541, 2023). "MAPK4 downregulation appeared to be an independent risk factor for poor prognosis in patients with gastric cancer." (PMID 36797541, 2023). "Kaplan‒Meier analysis revealed that lower expression of MAPK4 in gastric cancer tissues was significantly associated with reduced overall survival time of patients." (PMID 36797541, 2023). "Guo and his colleagues showed that the ectopic expression of miR-433 and miR-127 in gastric cancer cell lines inhibits cell proliferation, cell cycle progression, cell migration, and invasion by directly interacting with the mRNA encoding oncogenic factors KRas and MAPK4, respectively." (PMID 25477702, 2014). "TAMs activate the epithelial-mesenchymal transition of gastric cancer cells and inhibit the expression of MAPK4, creating a positive feedback loop that induces the secretion of MIF and contributes to TAM polarization." (PMID 40034694, 2025). "Collectively, these observations indicate that MAPK4 negatively regulates gastric cancer liver metastasis." (PMID 36797541, 2023). "MAPK4 downregulation in gastric cancer tissues from patients was found to be significantly associated with liver metastasis and poor prognosis." (PMID 36797541, 2023). "Taken together, these data suggest that TAMs activate EMT in gastric cancer cells to inhibit MAPK4 expression." (PMID 36797541, 2023). "The depletion of MAPK4 facilitates the invasion and metastasis of gastric cancer cells by polarizing TAMs in orthotopic mouse models." (PMID 36797541, 2023). "To determine the mechanism through which MAPK4 inhibits MIF secretion in gastric cancer cells, we examined the effects of MAPK4 expression on the protein or mRNA levels of MIF." (PMID 36797541, 2023). "Together, these results indicate that MAPK4 downregulation in gastric cancer cells promotes their invasion by activating TAMs." (PMID 36797541, 2023). "The forced expression of MAPK4 significantly decreases the liver metastatic capacity of gastric cancer cells." (PMID 36797541, 2023). "Taken together, our results suggest a previously undescribed positive feedback loop between cancer cells and macrophages mediated by MAPK4 silencing that facilitates gastric cancer liver metastasis." (PMID 36797541, 2023). "The depletion of MAPK4 in gastric cancer cells induced the secretion of macrophage migration inhibitory factor (MIF) to polarize TAMs in orthotopic xenograft tumors." (PMID 36797541, 2023). "MAPK4 depletion in gastric cancer cells induces the secretion of macrophage migration inhibitory factor (MIF) to polarize tumor-associated macrophages (TAMs) in orthotopic xenograft tumors." (PMID 36797541, 2023). "Multivariate analysis showed that MAPK4 expression in tumor tissues was an independent factor for predicting the prognosis of gastric cancer patients." (PMID 36797541, 2023). "Our data showed that the depletion of MAPK4 significantly increased the expression of MIF in gastric cancer cells and the percentage of CD206-positive macrophages in orthotopic tumors." (PMID 36797541, 2023). "Here, we employed an in vivo selection system to identify mitogen-activated protein kinase 4 (MAPK4) as a previously uncharacterized suppressor of gastric cancer liver metastasis in orthotopic mouse models." (PMID 36797541, 2023).
gastric cancer (continued). "To further explore the association of MAPK4 expression and EMT in gastric cancer tumors of patients, we employed tissue array analysis." (PMID 36797541, 2023). "The knockdown of MAPK4 in gastric cancer cells promotes liver metastasis in orthotopic mouse models." (PMID 36797541, 2023). "Here, we provide evidence showing that MAPK4 downregulation mediates a previously unrecognized positive feedback loop between cancer cells and TAMs in gastric cancer, which constitutes a “vicious cycle” to drive gastric cancer liver metastasis." (PMID 36797541, 2023). "TAM polarization further suppressed MAPK4 expression in gastric cancer cells, suggesting a hitherto undescribed positive feedback loop between cancer cells and macrophages in gastric cancer liver metastasis." (PMID 36797541, 2023). "RP11-3543B.1 exerts oncogene function via targeting miR-145-5p to regulate MAPK4 expression in gastric cancer cells." (PMID 34660601, 2021). "miR-127 has been shown to exert tumor suppressive functions in gastric cancers by interacting directly with the mRNA-encoding oncogenic factors KRAS and MAPK4." (PMID 27775664, 2016). "To determine whether macrophages mediate the function of MAPK4 in gastric cancer development, we generated a coculture model of gastric cancer cells and bone marrow-derived macrophages (BMDMs)." (PMID 36797541, 2023). "In orthotopic mouse models, MAPK4 downregulation in gastric cancer cells increases MIF secretion to activate TAMs, which activates cancer cell EMT to further inhibit MAPK4 expression, and these findings suggest a positive feedback loop between gastric cancer cells and TAMs to drive liver metastasis." (PMID 36797541, 2023). "Consistently, MAPK4 protein was also significantly decreased in gastric cancer tissues." (PMID 36797541, 2023). "Taken together, these results suggest that the tumor microenvironment may be essential for MAPK4 downregulation-induced gastric cancer cell invasion." (PMID 36797541, 2023). "We then examined the role of MAPK4 in gastric cancer cell invasion." (PMID 36797541, 2023). "To explore the mechanism through which MAPK4 downregulation promotes liver metastasis of gastric cancer, we tested whether MAPK4 influences the proliferation of gastric cancer cells." (PMID 36797541, 2023). "Furthermore, the relative levels of MAPK4 were significantly correlated with those of E-cadherin in gastric cancer tissues from patients." (PMID 36797541, 2023). "To further investigate whether MIF is responsible for TAM polarization and gastric cancer cell invasion induced by MAPK4 downregulation, we first examined MIF expression and TAM polarization in an orthotopic tumor model." (PMID 36797541, 2023). "The results showed that E-cadherin was significantly downregulated in tumor tissues compared with adjacent nontumor tissues and appeared to be an independent predictive factor of poor prognosis in gastric cancer patients, which was in agreement with our previous data on MAPK4 expression." (PMID 36797541, 2023). "To study how MAPK4 is downregulated in gastric cancer cells, we investigated whether TAMs inhibit MAPK4 expression." (PMID 36797541, 2023). "Moreover, TAMs activate epithelial–mesenchymal transition of gastric cancer cells to suppress MAPK4 expression, which further increases MIF secretion to polarize TAMs." (PMID 36797541, 2023). "In gastric cancer, miR-127 is significantly down-regulated and ectopic expression of miR-127 inhibits cell proliferation, cell cycle progression, cell migration and invasion by directly interacting with MAPK4." (PMID 32979257, 2020). "To determine whether MAPK4 downregulation promotes gastric cancer liver metastasis in orthotopic mouse models, we employed a lentivirus-based short-hairpin RNA (shRNA) to stably deplete MAPK4 expression in human gastric cancer cell lines, including BGC-823 and MKN45 cells." (PMID 36797541, 2023).